DNM2 (dynamin 2)
Description:
Catalyzes the hydrolysis of GTP and utilizes this energy to mediate vesicle scission at plasma membrane during endocytosis and filament remodeling at many actin structures during organization of the actin cytoskeleton. Plays an important role in vesicular trafficking processes, namely clathrin-mediated endocytosis (CME), exocytic and clathrin-coated vesicle from the trans-Golgi network, and PDGF stimulated macropinocytosis. During vesicular trafficking process, associates to the membrane, through lipid binding, and self-assembles into ring-like structure through oligomerization to form a helical polymer around the vesicle membrane and leading to vesicle scission. Plays a role in organization of the actin cytoskeleton by mediating arrangement of stress fibers and actin bundles in podocytes (By similarity). During organization of the actin cytoskeleton, self-assembles into ring-like structure that directly bundles actin filaments to form typical membrane tubules decorated with dynamin spiral polymers (By similarity). Self-assembly increases GTPase activity and the GTP hydrolysis causes the rapid depolymerization of dynamin spiral polymers, and results in dispersion of actin bundles (By similarity). Remodels, through its interaction with CTTN, bundled actin filaments in a GTPase-dependent manner and plays a role in orchestrating the global actomyosin cytoskeleton. The interaction with CTTN stabilizes the interaction of DNM2 and actin filaments and stimulates the intrinsic GTPase activity that results in actin filament-barbed ends and increases the sensitivity of filaments in bundles to the actin depolymerizing factor, CFL1 (By similarity). Plays a role in the autophagy process, by participating in the formation of ATG9A vesicles destined for the autophagosomes through its interaction with SNX18, by mediating recycling endosome scission leading to autophagosome release through MAP1LC3B interaction. Also regulates maturation of apoptotic cell corpse-containing phagosomes by recruiting PIK3C3 to the phagosome membrane (By similarity). Also plays a role in cytokinesis (By similarity). May participate in centrosome cohesion through its interaction with TUBG1 (By similarity). Plays a role in the regulation of neuron morphology, axon growth and formation of neuronal growth cones (By similarity). Involved in membrane tubulation.
Synonyms: DYN2; DYNII; CMTDIB; CMTDI1; DI-CMTB; CMT2M; LCCS5
Tractability: Small molecule: a high-quality ligand is known. Antibody: its Gene Ontology location is reachable by antibodies, with high confidence; UniProt places it where antibodies can reach, with medium confidence. PROTAC: ubiquitination databases record sites on it; its protein half-life has been measured; a small molecule that binds it is known.
Target class: Enzyme; Hydrolase
Gene: Protein-coding gene on chromosome 19 (10,717,974 to 10,833,504, forward strand). Ensembl gene ENSG00000079805.
Subcellular location: Cytoplasm, cytoskeleton; Cytoplasmic vesicle, clathrin-coated vesicle; Cell projection, uropodium; Endosome; Cytoplasm, cytoskeleton, microtubule organizing center, centrosome; Cytoplasm, cytoskeleton, microtubule organizing center, centrosome, centriole; Recycling endosome; Cell projection, phagocytic cup; Cytoplasmic vesicle, phagosome membrane; Cell projection, podosome; Cytoplasm; Cell junction; Postsynaptic density; Synapse, synaptosome; Midbody; Membrane, clathrin-coated pit
Subcellular location (Human Protein Atlas): Cytosol; Golgi apparatus
Pathways (Reactome):
Vesicle-mediated transport: Clathrin-mediated endocytosis; Formation of annular gap junctions; Gap junction degradation; Golgi Associated Vesicle Biogenesis; Lysosome Vesicle Biogenesis
Immune System: MHC class II antigen presentation; Toll Like Receptor 4 (TLR4) Cascade
Signal Transduction: NGF-stimulated transcription; Retrograde neurotrophin signalling
Cell-Cell communication: Degradation of CDH1
Developmental Biology: Recycling pathway of L1
Metabolism: NOSTRIN mediated eNOS trafficking
Gene Ontology:
Molecular function: GTPase activity; phosphatidylinositol-4,5-bisphosphate binding; protein binding; SH3 domain binding; enzyme binding; GTP binding; microtubule binding
Biological process: actin filament bundle organization; autophagy; endocytosis; membrane tubulation; negative regulation of membrane tubulation; protein polymerization; receptor internalization; receptor-mediated endocytosis; transferrin transport; vesicle scission; antigen processing and presentation of exogenous peptide antigen via MHC class II; centrosome cycle; G2/M transition of mitotic cell cycle; membrane organization; neuron projection morphogenesis; positive regulation of apoptotic process; positive regulation of DNA-templated transcription; post-Golgi vesicle-mediated transport; regulation of axon extension; regulation of DNA-templated transcription; signal transduction; stress fiber assembly; synaptic vesicle budding from presynaptic endocytic zone membrane; synaptic vesicle transport
Cellular component: centriole; centrosome; clathrin-coated vesicle; cytosol; endosome; extracellular exosome; focal adhesion; microtubule; postsynaptic membrane; recycling endosome; uropod; anchoring junction; clathrin-coated pit; cytoplasm; endocytic vesicle membrane; Golgi membrane; growth cone; midbody; neuron projection; plasma membrane; postsynaptic density; synapse; cytoskeleton; endomembrane system; membrane; and 4 more
Genetic constraint (gnomAD): Loss-of-function variants: 15 observed, 96.72 expected, observed/expected ratio (o/e) 0.16, 90% interval 0.1 to 0.24. The upper end of that interval is the gene's LOEUF score, 0.24, which puts it in group 1 of 6, group 1 being the genes least tolerant of losing a copy. Missense variants: 742 observed, 1,204.8 expected, observed/expected ratio (o/e) 0.62, 90% interval 0.58 to 0.65. Synonymous variants: 525 observed, 488.41 expected, observed/expected ratio (o/e) 1.07, 90% interval 1 to 1.15.
Gene-disease validity (ClinGen):
ClinGen rates the evidence that DNM2 causes each of these diseases.
autosomal dominant centronuclear myopathy (autosomal dominant): Definitive. An inherited neuromuscular disorder defined by numerous centrally placed nuclei on muscle biopsy and clinical features of a congenital myopathy.
Charcot-Marie-Tooth disease (autosomal dominant): Definitive. An inherited degenerative disorder involving the peripheral nerves.
Cancer hallmarks: proliferative signalling (promotes); invasion and metastasis (promotes); angiogenesis (promotes)
Homologues: Orthologues: macaque DNM2 (99% identical), chimpanzee DNM2 (99% identical), mouse Dnm2 (98% identical), pig DNM2 (97% identical), guinea pig DNM2 (96% identical), rat Dnm2 (95% identical), dog DNM2 (93% identical), tropical clawed frog dnm2 (90% identical), zebrafish dnm2a (85% identical), rabbit DNM2 (81% identical), zebrafish dnm3a (73% identical), zebrafish dnm2b (45% identical), and 1 more. Paralogues in human: DNM3 (79% identical), DNM1 (79% identical), DNM1L (36% identical), MX1 (23% identical), MX2 (21% identical), OPA1 (18% identical).
Diseases named in the same sentence as DNM2 in open-access papers:
DNM2 is named in the same sentence as 206 diseases in open-access papers, as found by Europe PMC text mining. Sharing a sentence is not in itself a finding about the gene and the disease. The quoted sentences say what the papers report.
centronuclear myopathy (85 papers, 2008 to 2026). Centronuclear myopathy (CNM) is an inherited neuromuscular disorder characterized by clinical features of a congenital myopathy and centrally placed nuclei on muscle biopsy. "Despite these hurdles, several studies are currently in preclinical development for disorders such as facioscapulohumeral muscular dystrophy, myotonic dystrophy and centronuclear myopathy due to DNM2 mutations." (PMID 39501809, 2024). "Compared to other centronuclear myopathies, those due to dominant DNM2 mutations tend to be less clinically severe." (PMID 39501809, 2024). "Most DNM2 mutations associated with centronuclear myopathy lead to reduced inhibition of its GTPase activity." (PMID 39501809, 2024). "Dynamin-2 (Dyn2), a large GTPase that regulates the polymerisation of actin, is known as a cause of autosomal dominant centronuclear myopathy (CNM)." (PMID 39451985, 2024). "While this manuscript was in preparation, a new study revealed that the R465W mutation in DNM2, which causes centronuclear myopathy, has been associated to an autophagy defect characterized by an impairment in autophagosome formation." (PMID 37060997, 2023). "For example, mutations in DYNAMIN1 (DNM1) cause epileptic encephalopathy, whereas DYNAMIN2 (DNM2) is found mutated in microcytic anemia, centronuclear myopathy, and Charcot-Marie-Tooth disease." (PMID 37060997, 2023). "Mutations in DNM2 cause autosomal dominant centronuclear myopathy (ADCNM), a rare disease characterized by skeletal muscle weakness and structural anomalies of the myofibres, including nuclear centralization and mitochondrial mispositioning." (PMID 35244154, 2022). "DNM2 mutations are the main cause of adult centronuclear myopathies, with disease onset sometimes reaching the 5th decade of age." (PMID 32456280, 2020). "Dominant DNM2 mutations cause different genetic diseases affecting different tissues: centronuclear myopathy (MIM #160150), Charcot-Marie-Tooth peripheral neuropathy (CMT; MIM #606482) and spastic paraplegia." (PMID 32809972, 2020). "Other skeletal muscle diseases with altered nuclear spacing notably include those caused by mutations in genes encoding nuclear envelope proteins, dynamin 2 (centronuclear myopathy) and skeletal muscle actin/nebulin (nemaline myopathy)." (PMID 33076971, 2020). "Mutations in the gene encoding for the GTPase Dynamin 2 (DNM2) cause a rare form of centronuclear myopathy (CNM), in which myonuclei are aberrantly located at the center of myofibers." (PMID 32503326, 2020). "Autosomal dominant mutations in the DNM2 gene cause centronuclear myopathy and dominant intermediate and axonal Charcot–Marie-Tooth disease." (PMID 32456280, 2020). "Autosomal dominant centronuclear myopathy (ADCNM) due to DNM2 mutations is characterized by progressive muscle weakness, mainly proximal, and facial weakness with ptosis." (PMID 32809972, 2020). "Mutations in DNM2 encoding dynamin-2 cause autosomal dominant centronuclear myopathy, which is associated with variable muscle weakness and wasting." (PMID 33330280, 2020). "Mutations in the DNM2 gene cause autosomal dominant centronuclear myopathy (CNM) and a knock-in mouse model expressing the most frequent human DNM2 mutation in CNM (Knock In-Dnm2R465W/+) develops a myopathy sharing similarities with human disease." (PMID 30733559, 2019). "Autosomal dominant mutations in the ubiquitously expressed DNM2 cause 2 discrete neuromuscular diseases: autosomal dominant centronuclear myopathy (ADCNM) and dominant intermediate Charcot–Marie–Tooth neuropathy (CMT)." (PMID 30426359, 2018). "Mutations in dynamin-2 cause dominant centronuclear myopathy (CNM), a congenital myopathy characterized by progressive weakness and atrophy of skeletal muscles." (PMID 28676641, 2017). "Mutations in DNM2 cause centronuclear myopathy (CNM), a rare hereditary disease characterized by centrally located nuclei in muscle fibres." (PMID 26842864, 2016).
centronuclear myopathy (continued). "Mutations in the dynamin-2 gene (DNM2) cause autosomal dominant centronuclear myopathy (CNM) and dominant intermediate Charcot-Marie-Tooth (CMT) neuropathy type B (CMTDIB)." (PMID 26842864, 2016). "Dynamin 2 mutations have previously been associated with other phenotypes including two forms of Charcot-Marie-Tooth neuropathy and centronuclear myopathy." (PMID 26517984, 2015). "Another DNM2-associated disease, autosomal-dominant Centronuclear myopathy, is a slowly progressive congenital myopathy characterized by delayed motor milestones, generalized muscle weakness, ptosis, and ophthalmoplegia." (PMID 26517984, 2015). "The association of DNM2 defects with human disease has been previously identified in Charcot–Marie-Tooth peripheral neuropathy 24 and centronuclear myopathy 25–27, both of which involve DNM2 gene loss-of-function mutations." (PMID 25092467, 2014). "DNM2, for example, is associated both with centronuclear myopathy, a congenital myopathy, and Charcot-Marie Tooth disease, a hereditary neuropathy." (PMID 25353622, 2014). "Mutations in DNM2 are a common cause of centronuclear myopathy, a severe disorder characterized by altered skeletal muscle structure and function." (PMID 24135484, 2014). "Mutations in dynamin-2 (DNM2) are the most common cause of autosomal-dominant centronuclear myopathy." (PMID 24135484, 2014). "Mutations in amphiphysin-2/BIN1, dynamin 2, and myotubularin are associated with centronuclear myopathy (CNM), a muscle disorder characterized by myofibers with atypical central nuclear positioning and abnormal triads." (PMID 25262827, 2014). "Over the last 8 years, more than 20 mutations in the dynamin-2 gene have been associated to two hereditary neuromuscular disorders: Charcot–Marie–Tooth neuropathy and centronuclear myopathy." (PMID 24065954, 2013). "Mutations in human DNM2 cause two distinct neuromuscular disorders: centronuclear myopathy and Charcot-Marie-Tooth disease." (PMID 23418470, 2013). "Mutations in myotubularin, amphiphysin 2 (BIN1), and dynamin 2 lead to different forms of centronuclear myopathy, while mutations in myotubularin-related proteins cause Charcot-Marie-Tooth neuropathies." (PMID 22496665, 2012). "DNM2 mutations have been linked to two autosomal dominant diseases: centronuclear myopathy (CNM) and the axonal or intermediate form of dominant Charcot-Marie-Tooth (CMT) disease." (PMID 22096584, 2011). "Mutations in both BIN1 and dynamin-2 result in centronuclear myopathy, a myopathy with similar pathologic features to myotubular myopathy." (PMID 19197364, 2009). "The fact that MTM-related proteins and DNM2 are mutated in both centronuclear myopathies and CMT neuropathies further points to a common mechanism involving PIs and membrane retrieval in skeletal muscle and peripheral nerve maintenance." (PMID 18429927, 2008). "Recurrent and de novo DNM2 mutations were originally identified following a positional candidate approach in 11 families with a mild form of autosomal-dominant centronuclear myopathy." (PMID 18817572, 2008). "Dominant DNM2 mutations cause a centronuclear myopathy that is clinically characterized by progressive distal and proximal weakness beginning during infancy or even young adulthood, as well as ptosis, ophthalmoparesis, facial weakness, dysphagia and respiratory insufficiency." (PMID 39501809, 2024). "Interestingly, three Vps1 mutants, I277G, G397R, and I442G, corresponding to DNM1 V235G, DNM2 G358R, and DNM2 V375G mutations found in microcytic anemia, Charcot-Marie-Tooth, and centronuclear myopathy, respectively, showed a defect in autophagic flux." (PMID 37060997, 2023). "Reduction of DNM2 was shown to rescue myotubular myopathy in mice (Mtm1−/y mice) by genetic cross or systemic delivery of antisense oligonucleotides (ASOs), or by reducing DNM2 using an adeno-associated virus-mediated shRNA approach targeting Dnm2." (PMID 35642830, 2022).
centronuclear myopathy (continued). "Heterozygous mutations in the DNM2 gene are responsible for autosomal dominant forms of three human diseases, i.e. centronuclear myopathy, Charcot-Marie-Tooth disease, and hereditary spastic paraplegia and one homozygous mutation was shown to cause a lethal congenital syndrome." (PMID 34294140, 2021). "BIN1 and DNM2, which encode a BAR domain protein BIN1 and dynamin 2, respectively, have been reported to be causative genes of centronuclear myopathy (CNM), a hereditary degenerative disease of skeletal muscle, and deformation of T-tubules is often observed in the CNM patients." (PMID 33187981, 2021). "Consequently, a consortium is testing its ASO candidate IONIS-DNM2–2.5Rx (DYN101) that is administered i.v. in patients with centronuclear myopathies caused by mutations in either DNM2 or MTM1 (NCT04033159)." (PMID 33324928, 2020). "In addition, NMJs are disrupted in preclinical models of centronuclear myopathy due to mutations in MTM1 or DNM2." (PMID 32804943, 2020). "A distal phenotype in NEB-associated nemaline myopathy and DNM2-associated centronuclear myopathy seems to be more common in late-onset CMs, and similarly a scapuloperoneal pattern may be also observed in late onset ACTA-1-related nemaline myopathy." (PMID 32456280, 2020). "A faithful mammalian model for severe centronuclear myopathy linked to DNM2 mutation." (PMID 32809972, 2020). "In this study, we tested allele-specific inactivation or correction of a heterozygous mutation in the Dynamin 2 (DNM2) gene that causes the autosomal dominant form of centronuclear myopathies (CNMs), a rare muscle disorder belonging to the large group of congenital myopathies." (PMID 30925452, 2019). "Autosomal dominant centronuclear myopathy is classically associated with mutations in DNM2 which codes for dynamin 2, a GTPase that is involved in the mechanisms of endocytosis and transport of organelles along the network of microtubules, and also plays a key role in centrosome formation." (PMID 29141652, 2017). "For example, in DNM2, mutations giving rise to a centronuclear myopathy phenotype are enriched in the interface between the middle domain and the pleckstrin homology domain, while mutations implicated in Charcot-Marie-Tooth disease tend to cluster in other parts of the pleckstrin homology domain." (PMID 25353622, 2014). "The underlying mechanism is still unclear, but it could explain the muscular dysfunction in centronuclear myopathies caused by dynamin-2 mutations." (PMID 24065954, 2013). "Furthermore, mutations in human DNM2 also cause two different neuromuscular disorders; Charcot-Marie-Tooth disease and centronuclear myopathy." (PMID 23418470, 2013). "In addition to centronuclear myopathy, dynamin 2 is also mutated in a dominant form of Charcot-Marie-Tooth neuropathy." (PMID 22496665, 2012). "In addition, BIN1 can tubulate membranes separately or in cooperation with dynamin 2 (DNM2), another protein mutated in centronuclear myopathy." (PMID 21797990, 2011). "The large GTPase dynamin 2 is a key player in membrane and cytoskeletal dynamics mutated in centronuclear myopathy (CNM) and Charcot-Marie Tooth (CMT) neuropathy, two discrete dominant neuromuscular disorders affecting skeletal muscle and peripheral nerves respectively." (PMID 22096584, 2011). "This hypothesis is sustained by the findings that DNM2 is also mutated in an autosomal dominant form of centronuclear myopathy and that mutations of amphiphysin 2 (BIN1) have recently been identified in patients with an autosomal recessive form of CNM." (PMID 18429927, 2008). "Monoallelic variants in DNM2 are associated with Charcot–Marie–Tooth disease and a rare form of congenital centronuclear myopathy (CNM)." (PMID 40259930, 2025). "Gain-of-function mutations of dynamin-2, a mechano-GTPase that remodels membrane and actin filaments, cause centronuclear myopathy (CNM), a congenital disease that mainly affects skeletal muscle tissue." (PMID 36142275, 2022).